SEMA4D (semaphorin 4D)
Diseases named in the same sentence as SEMA4D in open-access papers (continued):
Sharing a sentence is not in itself a finding about the gene and the disease.
cancer (continued). "In addition, mRNA and protein expression levels of β-catenin as an oncogenic transcription factor were, respectively, analyzed by RT-qPCR and Western blot to illustrate the mechanism underlying the decrease in cancer stemness and EMT markers through silencing of SEMA4D." (PMID 34337054, 2021). "SEMA4D may also be considered as a suitable target for treatment of cancers." (PMID 31205625, 2019). "Interestingly, higher nerve density in tumors expressing Sema4D suggests that these tumors may use nerve-secreted factors for growth, pointing to a possible role of Sema4D in cancer pain." (PMID 29971044, 2018). "Thus, there is a possibility that cancers in which Sema4D and PlexinB1 is expressed have enhanced invasive capacity through their control of the host immune response and that they may, as a consequence, cause a relapse." (PMID 27456345, 2016). "The differential function of Sema4D/plexin in tumour biology is also illustrated by the variable results in studies examining the expression levels of these molecules in the disease progression of human cancers with both low Sem4D and high plexin-B1, leading to poorer survival." (PMID 28536399, 2015). "In cancer zone B, the SEMA4 pathway relied on Sema4a-Plxnb2, Sema4d-Cd72, and Sema4d-Plxnb2 interactions, with Sema4a/d-Plxnb2 showing particularly strong communication between cancer_macro 1 cells." (PMID 40723284, 2025). "Sema4C, Sema4D, and Sema7A can be considered as promising biomarkers of TAM infiltration and can be used as prognostic indicators of cancer." (PMID 35155237, 2022). "To investigate if OPN plays a role in the regulation of Sema4D, we checked the basal level of OPN in HN6 and HN4 cancer cell lines, NOKSI, and potentially malignant cell lines DOK." (PMID 36338570, 2022). "However, the function of Sema4D on Treg responses in cancer is still unknown." (PMID 35155237, 2022). "Sema3E, Sema4D, and Sema7A were shown to contribute to EMT, whereas Sema3B, Sema3F, and Sema5A inhibited EMT in cancer cells." (PMID 35775491, 2022). "Semaphorin4D (SEMA4D), one of the members of SEMA IV subfamily, promotes angiogenesis in several cancers." (PMID 31105696, 2019). "Many cancer cells, including head and neck squamous cell carcinoma lines, express the membrane-tethered collagenase, MT1-MMP which cleaves Sema4D." (PMID 29971044, 2018). "If the osteoclast Sema4D axis is the only significant contributor to osteoblast suppression, then there may be little bone effect of treatment in patients also receiving anti-osteoclast drugs (bisphosphonates or denosumab), which are the standard of care for cancer bone diseases." (PMID 29971044, 2018). "Previous studies had identified SEMA4D and VEGF had a positive correlation in EOC cancer tissues and knockdown of VEGF could suppress SEMA4D expression, which indicate poor prognosis for EOC patients." (PMID 31105696, 2019). "Sema4D acts as a ligand for receptor plexins (B1, B2, and C1) and CD72 and has been reported to be involved in platelet and neutrophil activation, angiogenesis, and cancer metastasis." (PMID 30538782, 2018). "Sema4D fails to activate c-Met in melanomas, not because of a significant downregulation of plexin-B1 in these cancer cells." (PMID 23050142, 2012). "Although not shown in most studies involving cancer cell lines, another line of investigation of Sema4D and Plexin-B1 interactions centered on the collapse of neurite outgrowth." (PMID 20858260, 2010). "Immunofluorescence analysis of LM and CRC tissues from 36 patients further confirmed that SEMA4D was significantly overexpressed in LM and CRC tissues compared with healthy colon tissue samples; additionally, CD8 was significantly downregulated in these cancer samples." (PMID 39443302, 2024). "A major open question is whether Sema4D from non-osteoclast sources plays a significant role to inhibit osteoblast activity in cancer/bone diseases." (PMID 29971044, 2018).
cancer (continued). "Targeting Sema4D in these cancers would not affect bone remodeling and therefore could elicit an improved therapeutic result without the debilitating side effects." (PMID 26910109, 2016).
infection (6 papers, 2017 to 2024). The state of being infected such as from the introduction of a foreign agent such as serum, vaccine, antigenic substance or organism. "The results showed that GPS infection significantly decreased the expression levels of Sema4D and PlexinB1 (p < 0.05), whereas quercetin increased the expression levels of these angiogenetic genes to a normal level." (PMID 38927100, 2024). "Sema4D co-localised with HSCs marker (GFAP) revealed that Sema4D in HSCs was significantly increased in mice livers after infection with S. japonicum and could be reduced by treated with HBAAV2/9-Sja-miR-71a (arrows)." (PMID 32944173, 2020). "Taken together, these experiments showed that Sema4D was markedly increased after infection with S. japonicum, and Sja-miR-71a could inhibit Sema4D expression by directly interacting with its 3′-UTR." (PMID 32944173, 2020). "The results showed that Sema4D and PlexinB1 were significantly downregulated after 72 h of GPS infection (p < 0.05)." (PMID 38927100, 2024).
neurodegenerative disease (5 papers, 2020 to 2024). A disorder of the central nervous system characterized by gradual and progressive loss of neural tissue and neurologic function. "To determine if SEMA4D upregulation is common to underlying pathology in another neurodegenerative disease in addition to HD, we evaluated postmortem brain sections from subjects with AD." (PMID 35933420, 2022). "Altogether, these findings support the immunomodulatory properties of SEMA4D in translational rodent models of inflammation-associated neurodegenerative diseases, including HD." (PMID 32161599, 2020). "Sema4D indirectly costimulates T cells, compromises blood–brain barrier, activates microglia, and inhibits remyelination in neurodegenerative diseases." (PMID 38664244, 2024). "We report here that SEMA4D is upregulated in neurons during progression of neurodegenerative diseases and is a trigger of reactive astrocytes." (PMID 35933420, 2022). "Collectively, these findings support the therapeutic potential of SEMA4D antibody blockade to regulate glial cell function and reduce neuronal toxicity and dysfunction in neurodegenerative diseases including HD and AD." (PMID 35933420, 2022). "Previous studies in rodents have demonstrated the efficacy of SEMA4D activity blockage in several disorders, including neurodegenerative diseases." (PMID 32161599, 2020). "Results suggest that blockade of SEMA4D signaling may serve to normalize astrocytic functions and slow astrocyte reactivity that is believed to contribute to pathology and symptoms of neurodegenerative disease." (PMID 35933420, 2022). "Here, we characterize SEMA4D expression in neurodegenerative disease settings of HD and AD, and report SEMA4D-induced changes in cytoskeletal morphology and regulation of key receptors and enzymes required for normal astrocytic functions in glucose metabolism and neurotransmitter recycling." (PMID 35933420, 2022). "In order to investigate whether this pathogenic mechanism may be more broadly relevant to slowly progressive neuroinflammatory/neurodegenerative diseases, we here extend the analysis of SEMA4D expression, astrocyte morphology and regulation of GS expression to human autopsy sections from AD brain." (PMID 35933420, 2022).
cardiovascular disease (4 papers, 2020 to 2025). "Recently, Sema4D has been reported to exert a proinflammatory effect on the endothelium and to be involved in cardiovascular disease." (PMID 33381571, 2020). "Sema4D offers a novel and promising target to mitigate calcification in cardiovascular diseases." (PMID 40507881, 2025).
infectious disease (3 papers, 2013 to 2018). A disorder directly resulting from the presence and activity of a microbial, viral, or parasitic agent in humans. "CD100/Sema4D has been demonstrated to play an important role in physiological and pathological immune responses, but the functional role of CD100 in infectious diseases has only been inadequately reported." (PMID 24040126, 2013).
central nervous system diseases (2 papers, 2024). "rs913807 was mapped to SEMA4D, which was a key factor in central nervous system diseases." (PMID 39300745, 2024).
retinopathy (2 papers, 2020 to 2022). "By performing a comprehensive analysis of the semaphorins family, we identified the increased expression of Sema4D during oxygen‐induced retinopathy (OIR) and streptozotocin (STZ)‐induced retinopathy." (PMID 31943789, 2020). "Moreover, anti-Sema4D and anti-VEGF antibodies have synergistic effects in inhibiting retinal neovascularization and vascular leakage, indicating the promising potential of Sema4D as a therapeutic target for retinopathy." (PMID 35045890, 2022). "By performing a comprehensive analysis of the semaphorins family, we identified an increased expression of Sema4D during oxygen‐induced retinopathy (OIR) and streptozotocin (STZ)‐induced retinopathy." (PMID 31943789, 2020).
hematologic cancers (1 paper, 2022). "A prior investigation into hematologic cancers found that SEMA4D is present in virtually all CLL cells and is crucial in sustaining CLL cell survival and proliferation." (PMID 35794581, 2022).
SEMA4D also shares sentences with these, for which no sentence is quoted: neurological disorders (6 papers); non-small cell lung carcinoma (4); acute myocardial infarction (3); esophageal squamous cell carcinoma (3); multiple myeloma (3); viral infection (3); bladder cancer (2); diffuse large B-cell lymphoma (2); endothelial dysfunction (2); hepatitis C virus (2); immune dysfunction (2); meningioma (2); Miscarriage (2); Parkinson disease (2); systemic sclerosis (2); T cell lymphomas (2); uveal melanoma (2); acute kidney injury (1); acute promyelocytic leukemia (1); aneurysm (1); Atherosclerotic lesion (1); bone density (1); cataract (1); Cerebral ischemia (1); chronic hepatitis (1); chronic hepatitis B (1); chronic hepatitis C virus infection (1); cognitive decline (1); cognitive deficits (1); coronary artery diseases (1).
A further 41 diseases each share a sentence with SEMA4D in 1 paper.